TNF (tumor necrosis factor)
Diseases named in the same sentence as TNF in open-access papers (continued):
Sharing a sentence is not in itself a finding about the gene and the disease.
breast carcinoma (continued). "In turn, oestrogens themselves up-regulate transcription and secreted levels of TNF-alpha in ER+ breast cancer cells, therefore creating an autocrine-positive feedback loop." (PMID 38332913, 2023). "TNF-α was also one of the most commonly reported biomarkers in breast cancer trials, and nine different studies discussed its use as an indication with clinical relevance." (PMID 37181043, 2023). "Estrogen deprivation in cultured BM stromal monolayers induces the secretion of IL-6 and IL-8, activates TGFβ and TNFα signaling and promotes the growth of breast cancer colonies." (PMID 37296983, 2023). "PrPC silencing has been shown to sensitize breast cancer cell lines to TRAIL-, Bax, TNF-α, and adjuvant chemotherapy-mediated cell death, which can also be considered as alternative treatments in breast cancer." (PMID 37894349, 2023). "In particular, prolonged exposure of breast cancer cell lines to TNFα induces EMT through the activation of IKKβ and NF-κB, cancer cell migration via the MAPK/ERK signaling pathway, and MMP2 and MMP9 expression." (PMID 36835413, 2023). "Significant correlations between ER-alpha, TNF-alpha and NF-kB expression have been shown in breast cancer tissues." (PMID 38332913, 2023). "In a previous study, we identified the enrichment of TNFα signaling via NF-κB in CTC cultures derived from breast cancers." (PMID 36980717, 2023). "Regarding unique markers, CA15-3 and TNF-alpha were two of several breast cancer-specific, and CA19 and IL-18 were pancreatic cancer-specific." (PMID 37181043, 2023). "Astrocytes were demonstrated to support lung and breast cancer cells metastasis by producing interleukin-1 beta (IL1β) and tumor necrosis factor-alpha (TNFα)." (PMID 36835266, 2023). "Anticancer drugs increase TNF-α expression, which results in the activation of the immune system and the destruction of breast cancer cells." (PMID 37108425, 2023). "Cancer and stromal cells in the microenvironment of breast tumors also show increased levels of TNF-α, which induces NF-κB activation and enhances the proliferation of breast cancer cells, cell survival and metastasis." (PMID 38201482, 2023). "The results of Meng’s meta-analysis showed a significant reduction in IL-2, IFN-γ, IL-6, IL-1β, and TNF-α levels in breast cancer patients participating in the Qigong practice group." (PMID 36831519, 2023). "For instance, TNF-α has been identified as a proinflammatory cytokine in the tumor microenvironment that influences different stages of breast cancer progression and patient survival conditions." (PMID 37212877, 2023). "TNFα can induce resistance to breast cancer therapies, such as ionizing radiation therapy and chemotherapy." (PMID 36835413, 2023). "We focused on targeting TNF-α signaling in a syngeneic BALB/c mouse model using 4T1 breast cancer cells with Infliximab, a monoclonal antibody against TNF-α." (PMID 38201482, 2023). "TNF-α binds to TNFR in breast cancer cells and activates MAPK/ERK and NF-kB, and IL-1β secreted by adipocytes binds to IL-1R and upregulates and activates NF-kB and CREB via its receptor IL-1R." (PMID 37296983, 2023). "Attenuating TNF-α signaling decreased the activation of the autotaxin–lysophosphatidate–inflammatory cycle, which provides a strategy for decreasing breast cancer metastasis." (PMID 38201482, 2023). "Decreasing TNF-α signaling in this aggressive 4T1 breast cancer model decreased NF-κB activation and the expression of inflammation-related genes that regulate metastasis." (PMID 38201482, 2023). "The presence of programmed death ligand 1 (PD-L1), macrophage-derived TNF-α, antibiotics, or chemotherapy can induce pyroptosis by the caspase-8/GSDMC pathway, and TNF-α can induce pyroptosis through GSDMC in MDA-MB-231 breast cancer cells." (PMID 36605484, 2023). "The knockdown of SMG7 in breast cancer cells decreased the effectiveness of TNFα-mediated cell death." (PMID 37349371, 2023).
breast carcinoma (continued). "Previous studies have shown that CEACAM1 possesses an ISRE in its promoter region and is synergistically induced by TNFα and IFNγ in endothelial cells, colorectal carcinoma cells, cervix carcinoma cells, and breast carcinoma cells." (PMID 37691945, 2023). "Exogenous TNF-α has been shown to promote breast cancer cell migration accompanied by an increased secretion of MMP9, as well as upregulate the expression of CD26 and FAP-α in a dose-dependent manner." (PMID 36937451, 2023). "Blocking TNF-α signaling with Infliximab, a monoclonal antibody, decreased breast cancer metastasis to lungs in mice by ~60%." (PMID 38201482, 2023). "TNF-α, NF-κB signaling and ATX expression are positively linked to each other in breast cancer patients, and this pathway plays a role in increasing the clonogenicity of breast cancer cells." (PMID 38201482, 2023). "Studies in vitro showed that TNF-α-induced NF-κB activation increases autotaxin expression and the clone forming ability of 4T1 breast cancer cells." (PMID 38201482, 2023). "TNF-α treatment has been reported to inhibit proliferation and induce apoptosis in some breast cancer cell lines." (PMID 37138170, 2023). "TNF-α has a dual role in breast cancer, and its effects are mainly regulated depending on concentrations in the tumor and the TME, and this is responsible for breast cancer cell survival or cell death." (PMID 38201482, 2023). "PTGS2 expression is induced by PGE2 and the inflammatory cytokine TNF-α, promoting the development of breast cancer in patients with CD." (PMID 37138170, 2023). "TNF-α is a major inflammatory cytokine in the tumor microenvironment, and its levels are increased in metastatic breast cancers to adversely affect disease progression." (PMID 38201482, 2023). "In vivo, the release of interferon-α (IFN-α) and TNF-α has been shown in astrocytes forming gap junctions with lung and breast carcinoma cells, supporting tumor growth." (PMID 37749707, 2023). "The immune-related vitamin K-dependent glycoprotein encoded by PROS1 is synthesized in the liver and is a tumor suppressor that can inhibit metastasis by suppressing the TNF-alpha pathway in lung and breast cancers." (PMID 37063858, 2023). "In both training and validation cohorts, we found that the riskscore for IL-4 and TNF-α had a detrimental effect on overall survival in breast cancer." (PMID 37007080, 2023). "TNF-α is one of the most important pro-inflammatory cytokines in breast cancer TME, which is secreted by stromal cells (mainly M1 TAM) and cancer cells themselves." (PMID 37007080, 2023). "Given the significant role of TNF-α, use of probiotic supplementation would appear warranted to reduce cancer severity and/or symptoms and provide improvement in prognosis for both breast cancer patients and survivors." (PMID 36829557, 2023). "TNF-α has been shown to drive increased proliferation of breast cancer cells and suppression of the host immune response against a developing tumor." (PMID 36829557, 2023). "Our results found that breast cancer survivors with psychological distress showed significantly higher levels of IL‐1β, TNF‐α, and IL‐4." (PMID 36965094, 2023). "In breast cancer, PrP exhibits an antiapoptotic effect on the cytotoxic action of tumor necrosis factor α (TNF) and contributes to TNF-resistance." (PMID 37535656, 2023). "In the current study, we report that the inhibition of TNF-α signaling in a syngeneic mouse model of breast cancer using Infliximab inhibited metastasis to the lungs by inhibiting NF-κB and LPA-ATX signaling." (PMID 38201482, 2023). "The primary factor in the breast cancer microenvironment is TNF-α, which is an important pro-inflammatory cytokine, primarily released by the tumour-associated macrophages and the cancerous cells." (PMID 37742025, 2023).
breast carcinoma (continued). "TNF-α can be produced by both the breast cancer cells and immune cells in the TME, which regulates diverse processes such as cell–cell communication, proliferation, differentiation and metastasis and cell death." (PMID 38201482, 2023). "Despite intensive research into TNF-α-induced effects in breast cancer biology, details of the molecular mechanisms of TNF-α action remain largely unexplored." (PMID 38201482, 2023). "The TNF-α-activated NF-κB pathway is a one of the major inducers of inflammatory cytokines in breast cancer." (PMID 38201482, 2023). "TNF-α was the second most frequently inflammatory cytokine mentioned by studies in this review related to breast cancer." (PMID 37181043, 2023). "The ability of HDL to inhibit IL6 and TNF production was higher in breast cancer compared to controls, especially in advanced stages of the disease." (PMID 37628945, 2023). "Specifically, berberine reduces the expression of TNFα and IL-6 as well as inhibits c-Jun, c-Fos and NF-κB signaling in breast cancer cells." (PMID 36670988, 2023). "In the apoptotic signaling pathway of breast cancer cells, tumor necrosis factor (TNF) mediates the extrinsic pathway for intra- and extracellular signaling." (PMID 37542283, 2023). "In particular, prolonged exposure to TNF-α in breast cancer cell lines induces upregulation of the transcriptional repressor Twist1 through activation of IKKβ and NF-κB, induces EMT, and enhances CSC properties." (PMID 37138170, 2023). "Osteoblasts can also protect breast cancer cells from chemotherapy by inducing a dormancy state, notably due to the secretion of cytokines such as tumor necrosis factor α (TNFα) and monocyte chemoattractant protein-1 (MCP1)." (PMID 37182144, 2023). "In breast cancer, other cytokines such as IL‐6, IL‐1α, IL‐1β, IL‐8, TNF‐α/β, TGF‐β, and GM‐CSF are also known to stimulate angiogenesis." (PMID 36815234, 2023). "Hou’s group found that Caspase-8 can cut GSDMC in hypoxic breast cancer cells, and its expression level was mediated by the PD-L1, following by TNF-α induced pyroptosis." (PMID 37359371, 2023). "The role of TNF-α in regulating ATX expression in breast cancer was further validated in the tumor tissues of Infliximab-treated mice." (PMID 38201482, 2023). "In turn, breast cancer cells release TNF-α, activate mTORC1/FOXK1 in TAMs and stimulate M2 polarization with elevated release of CCL2, thereby forming a positive feedback mechanism and offering therapeutic resistance." (PMID 37900137, 2023). "Enrichment analysis results showed that the enrichment pathways also differed among different breast cancer subtypes, with some pathways related to immunity, such as T cell receptor complex, TNF signalling pathway and Salmonella infection." (PMID 37353728, 2023). "It is worth noting the proposition that the p38-MNK1-PML network regulates TNFα-induced apoptosis in breast cancer cells and TNFα-mediated inhibition of migration and capillary tube formation in endothelial cells." (PMID 38069029, 2023). "Inflammation-related pathways, including increased TNF-α signaling, were commonly activated in both tumor xenografts and breast cancer cell lines when exposed to hyperglycemia." (PMID 37906280, 2023). "In mouse models of breast cancer, tramadol attenuated tumor growth and hormone receptor expression, reduced the serum level of TNF-α, and preserved the NK cell activity compared with morphine." (PMID 36765695, 2023). "This conclusion is supported by previous studies indicating the mutual suppression between NFκB/TNF and ER/PR in breast cancer." (PMID 37475016, 2023). "Linoelaidic acid at the dose of 5 μM/ml, can markedly rise in TNF-α and IL-1ra level in breast cancer cells." (PMID 37644076, 2023). "In contrast, VSMCs were treated with BC-CM from RGS5 knockdown breast cancer cells reversed the upregulation of TNF-α, VCAM-1 and macrophages adhesion." (PMID 37986113, 2023).
breast carcinoma (continued). "Together, these results show that TNF-α-induced NF-κB activation increases limited ATX expression in breast cancer cells, and LPA production increases clonogenicity." (PMID 38201482, 2023). "al., a 16-week aerobic and resistance exercise intervention decreased TNF-α among obese postmenopausal breast cancer survivors." (PMID 37181043, 2023). "The activities of cancer-associated fibroblasts (CAFs) and mesenchymal stromal cells (MSCs) in breast cancer are integrated within an intimate inflammatory tumor microenvironment (TME) that includes high levels of tumor necrosis factor α (TNF-α)." (PMID 37681908, 2023). "Concerning resistance training, it appears to help female breast cancer survivors to decrease TNF-α production by their NK and natural killer T (NKT) cells." (PMID 36612320, 2023). "In a mouse mammary tumor model, when taken up by T cells, linoleic acid was shown to promote naïve T-cell apoptosis and inhibit TNF-α production." (PMID 37492568, 2023). "In female dogs with mammary tumor, it was found that the highest gene expression of IL-6 and TNF-α was associated with worst prognoses with an inverse correlation between TNF-α and survival time." (PMID 37410738, 2023). "Low doses of TNFα promote tumor growth and angiogenesis in mouse models of melanoma, lung cancer, and mammary tumors." (PMID 36996146, 2023). "It has been reported that cytokines, IFNs, and TNFα regulate the inducible expression of PD-L1 on breast cancer and immune cells." (PMID 35053979, 2022). "In this study, we showed that ginsenoside Rh2 can initiate TNFα-induced apoptosis of breast cancer cells via ERβ." (PMID 35593465, 2022). "TNF‐α is a proinflammatory cytokine that is upregulated in breast cancer and correlates with breast cancer progression and recurrence." (PMID 34197030, 2022). "According to our KEGG analysis, 15 hub genes were involved in the cancer pathway, IL-17 signaling pathway, TNF signaling pathway, breast cancer, and estrogen signaling pathway." (PMID 36405393, 2022). "TNF-α induces autophagy in various cancer cell types, such as Ewing sarcoma, human breast cancer, and human T lymphoblastic leukemia cells." (PMID 36559076, 2022). "We also investigated the role of Bcl-3 in the response to TNF stimulation in other cell types, including colon cancer cells and breast cancer cells." (PMID 34853447, 2022). "Whereas BV6, in synergy with TRAIL and TNFα treatment, worsens the morphology of both breast cancer cells." (PMID 36358282, 2022). "In a recent study, DIM was evaluated against MCF‐7 breast cancer cells, and it was reported that DIM significantly reduced the TNF‐α/TGF‐β‐induced breast cancer cells migration." (PMID 35384373, 2022). "It seems that Th17 cells by creating inflammatory conditions through the secretion of cytokines, including IL-22, IL-17, TNF-α, IL-21, and IL-6, can significantly enhance breast cancer progression." (PMID 35248028, 2022). "An estrogen dependent regulation of soluble extracellular TNF and TNF-R2 was corroborated in experimental ER+ breast cancer in mice." (PMID 35432372, 2022). "A previous study investigating the effect of E2 on MCP-1 expression in breast cancer cell lines reported that E2 induced MCP-1 expression when the cells were pre-treated with TNF-α." (PMID 36142876, 2022). "An experiment conducted by Lei Hu proved that breast cancer cells were stimulated to undergo pyroptosis via BAK or BAX/caspase-3/GSDME axis with the treatment of TNFα+CHX and navitoclax." (PMID 36119049, 2022). "Alternatively, BP1 transcriptionally activates bcl-2 and inhibits tumor necrosis factor (TNF)-α-induced cell death in MCF7 breast cancer cells." (PMID 35883028, 2022).
breast carcinoma (continued). "Most existing studies on the effects of exercise on inflammatory factors and IGF systems in breast cancer survivors examine IL-6, IL-10, IL-1β, TNF-α, CRP, IGF-1, and IGFBP-3 levels." (PMID 36482346, 2022). "A recent clinical study demonstrated that KD therapy played a beneficial role by reducing TNF- α, and insulin, and increasing IL-10 in breast cancer patients." (PMID 36438725, 2022). "The shift from cellular dormancy to cell proliferation was also evident through bone TME remodeling by interleukin-6 (IL-6) and the tumor necrosis factor-alpha (TNFα) in metastatic breast cancer cells." (PMID 36430404, 2022). "In their experiment, proliferation of the hTNFα-induced MCF-7 breast cancer cell line was inhibited by TNFα-specific nanobody." (PMID 35933373, 2022). "Given the link between inflammation and cancer, it is not unexpected that an increasing number of studies documents TNF‐α as a tumor promoter in breast cancer, supporting the notion that TNF‐α is important for breast cancer progression." (PMID 34197030, 2022). "HER-2/neu overexpressing breast cancer cells are typically resistant to the cytotoxic effects of TNF." (PMID 36066630, 2022). "TNF signaling has been shown to be relevant for breast cancer tumor progression and metastasis as well as acquired drug resistance." (PMID 36130940, 2022). "In this context, the current study investigates the alteration of TNF-α and IL-19 at different clinical disease stages, lymph node metastasis, and ductal carcinoma in women with breast cancer." (PMID 35928364, 2022). "SMAC mimetic BV6 induces cell death, inhibits autophagy, and sensitizes breast cancer cell lines to TNF-α and TRAIL-induced apoptosis." (PMID 36358282, 2022). "Both IFNα2 and TNFα levels were significantly high in breast cancer patients with high PD-L1 levels." (PMID 35053979, 2022). "Even at a lower concentration, curcumin significantly leads to promising results against cell viability of MCF-7ADR (±6%) and Tumor Necrosis Factor resistant BT-20TNF breast cancer (8%) cell lines." (PMID 36143462, 2022). "Sensitivity analysis showed that exercise had a significant effect on TNF-α levels in breast cancer survivors after excluding highly heterogeneous studies." (PMID 36482346, 2022). "The putative mode of action is sensitization of HER-2/neu overexpressing breast cancer cells to TNF-therapy and subsequent induction of apoptosis through the direct effects of TNF on tumor cells." (PMID 36066630, 2022). "On the other hand, TNF-alpha is an important pro-inflammatory cytokine in the tumor microenvironment and is secreted both by breast cancer and by surrounding stromal cells." (PMID 35365723, 2022). "The adjusted HR (95% CI) was significantly lower in the TNF inhibitor cohort than the nbDMARD cohort for gastrointestinal cancer (0.432; 0.235–0.797), breast cancer (0.146; 0.045–0.474), and genitourinary cancer (0.220; 0.059–0.820)." (PMID 35945635, 2022). "TNF-α is rarely detected in healthy women’s serum, while it exists in high levels in breast cancer patients." (PMID 36140220, 2022). "TNF-α is highly increased in breast cancer, and its expression significantly correlated with the migration, invasion, and metastasis of breast cancer cells." (PMID 35440077, 2022). "COPS5 is required for TNF-α-mediated PD-L1 stabilization in breast cancer cells and inhibition of COPS5 sensitized cancer cells to anti-CTLA4 therapy." (PMID 36304306, 2022). "We tested a library of 31 ion channel targeting compounds for their effect on kynurenine production by TNF/IFN-ɣ stimulated human breast cancer MDA-MB-231 and lung cancer A549 cells." (PMID 35150740, 2022).